SIRT1 (sirtuin 1)
Diseases named in the same sentence as SIRT1 in open-access papers (continued):
Sharing a sentence is not in itself a finding about the gene and the disease.
tumor (continued). "By transient transfection of CRC cells with Sirt1-ASO, we demonstrated that the anti-tumor effects of resveratrol on cells was abolished, suggesting the essential role of this enzyme in the resveratrol signaling pathway." (PMID 26959057, 2016). "The opposite regulation has also been reported, e.g. inhibition of SIRT1 leads to acetylation and degradation of PKM2 while stimulating tumor proliferation." (PMID 27494892, 2016). "In our study, high Beclin-1 expression was significantly correlated with tumor size (p = 0.001), histological grade (p < 0.001), LN metastasis (p < 0.001), TNM stage (p < 0.001), VCE (p = 0.013), and high SIRT1 expression (p < 0.001)." (PMID 28070138, 2016). "However, the exact effect of MSCs overexpressing Sirt1 on tumor development remains unclear." (PMID 27764779, 2016). "When ERβ is activated by the selective agonist KB9520, SIRT1 and FOXM1 are down regulated, resulting in increased acetylated AKT1 and interaction with PARP1, HSC70 and GADPH in tumor cells, both in vitro and in vivo." (PMID 26885609, 2016). "Univariate Cox proportional hazard analysis showed that large tumor size, poor histological grade, positive LN metastasis, advanced GC, high TNM stage, high SIRT1, and Beclin-1 expression were significantly related to shorter OS and RFS (p < 0.05)." (PMID 28070138, 2016). "Correspondingly, the antitumor effect of MSCs-Sirt1 can be greatly impaired after IFN-γ or NK cells depletion, suggesting that IFN-γ and NK cells are essential for the MSCs-Sirt1-induced tumor inhibition." (PMID 27764779, 2016). "Next, we investigated the functional impact of SIRT1 in MEK1-induced self-renewal and tumor initiating ability." (PMID 26967560, 2016). "We have further shown that SIRT1 is essential for KSHV-induced cellular transformation, and an inhibitor of SIRT1, nicotinamide (NAM), inhibits tumor progression and extends the survival of mice in a xenograft model of KSHV-induced tumorigenesis." (PMID 27708228, 2016). "Silencing SIRT1 also suppresses non-small cell lung cancer (NSCLC) cell proliferation, induces senescence in a p27Kip1-dependent manner and dramatically suppresses tumour formation and proliferation in two distinct NSCLC xenograft mouse models." (PMID 27793039, 2016). "The aim of this paper was to determine the mechanisms by which resveratrol suppresses tumor cell growth and metastasis in CRC cells by targeting Sirt1 protein and regulating the NF-κB signaling pathway." (PMID 26959057, 2016). "High SIRT1 and SIRT2 protein levels were found in NSCLC cell lines compared with non-tumor lung epithelial cells." (PMID 25915617, 2015). "Although CoREST1 has been identified in complexes with factors that promote tumor progression, such as LSD1, ZNF217, ZNF198, HDAC1/2 and SIRT1, the role of CoREST1 in tumorigenesis is unclear." (PMID 25793264, 2015). "It has already been demonstrated for SIRT1-3 and SIRT6 that they have the potential to function as both tumour suppressor and promoter not only within different tumour types, but also within tumours of the same tissue origin." (PMID 26121130, 2015).
tumor (continued). "Taken together, these results suggest that metformin activated AMPK and increased the expression of SIRT1 significantly, parallel to CRD both in the tumor and in the host tissue." (PMID 25895126, 2015). "Together, these data suggest that regulation of miR-34a-SIRT1 axis in BCSCs inhibited tumorigenesis and decreased ALDH1-positive cell population resulting in suppression of tumor growth in xenograft mice." (PMID 25826085, 2015). "The median percentages of positive tumor nuclei, used for the statistical analyses, were 85% for LSD1, 80% for HDAC2 and 70% for SIRT1." (PMID 25139823, 2014). "Analyses of paired tumor and normal tissues showed an increased expression of LSD1 and SIRT1 in tumor tissues compared to normal tissues (both p < 0.001)." (PMID 25139823, 2014). "Regulation of rRNA expression by SIRT1 and of histone methylation by PRC2 as well as the WNT signaling pathways are specific targets that distinguish healthy and tumor cells." (PMID 27600345, 2014). "Although the precise mechanism of tumor suppression by CPEB1 is still undetermined, we found that HES1 and SIRT1 were targets of CPEB1-mediated translational control." (PMID 25216517, 2014). "In this study, we demonstrated for the first time that SIRT1 is a critical negative regulator of EMT and cell migration in vitro, and also of tumor metastasis in vivo (immunodeficient mouse model)." (PMID 25424420, 2014). "Therefore, we hypothesize that the complex of LSD1, HDAC2 and SIRT1 has important roles, next to chromatin repression, in regulating cell survival and that aberrant expression of this complex leads to sustained survival of tumor cells." (PMID 25139823, 2014). "Our research demonstrated higher rates of tumor recurrence and worse OS in patients with high LVD, positive LVI and SIRT1 positive expression." (PMID 25922660, 2014). "Moreover, whether SIRT1 acts as a tumor promoter or tumor suppressor remains controversial." (PMID 25522783, 2014). "The association between high Sirt1 expression and poor histological grade may also explain why in our cohort Sirt1 expression is associated with poor outcome regardless of the tumor stage as shown by its prognostic independency in multivariate survival analysis." (PMID 24088390, 2013). "Sirtuin 1 (Sirt1), a class III nicotinamide adenine nucleotide (NAD+)-dependent histone/protein deacetylase, has been reported to be a key target of Res in several tumor models." (PMID 24278101, 2013). "It has been reported that SIRT1, SIRT2, SIRT3, SIRT4 and SIRT6 appear to act as tumor suppressors in certain conditions." (PMID 23846322, 2013). "It was also noted that the inhibition of SIRT1 with NAM sensitized the MCF-7 cells to drug treatment only at low concentrations, demonstrating that the activated SIRT1 pathway promoted tumor cell survival through its deacetylase activity." (PMID 24137378, 2013). "We sought to exploit the predictable kinetics of the MYC/DDC tumor model system to determine the relationship of MYC and SIRT1 in vivo." (PMID 23024800, 2012). "Our data demonstrate that SIRT1 and SIRT3 coordinately regulate fatty acid synthesis in tumor cells." (PMID 22768255, 2012). "However, it remains unclear whether SIRT1 functions as an oncogene or tumor suppressor." (PMID 23024800, 2012). "These tumor suppressive effects of miR-34a are mediated by changes in a number of target mRNAs including MYCN, CDK4, cyclin D1, SIRT1 and Bcl-2." (PMID 22629428, 2012). "In order to investigate the role of SIRT1 in liver tumorigenesis we utilized bitransgenic Tet-O-MYC mice (Tet-O-MYC mice) and primary culture tumor cells (Tet-O-MYC cell) derived from established liver tumors." (PMID 23024800, 2012).
tumor (continued). "In this study, we identify SIRT1 as a deacetylase that antagonizes p300/CBP and deacetylates β-catenin, thus slowing cellular proliferation and tumor growth in vivo." (PMID 18414679, 2008). "Given the context‐dependent functions of SIRT1 in NSCLC, direct inhibition of SIRT1 may yield paradoxical outcomes contingent on the tumor's genetic landscape and microenvironment." (PMID 40855785, 2026). "Furthermore, the MALAT1/miR-124/SIRT1 axis regulates pyroptosis, while transcription factor TCF3 activates SIRT1 to trigger Wnt/β-catenin signaling and tumor growth." (PMID 41471349, 2025). "Cellular RIPK1-caspase-8-dependent apoptosis was enhanced by the use of SIRT1 inhibitors, suggesting that RIPK1 may promote apoptosis upon acetylation, thus affecting the biological behavior of tumor cells and influencing tumor development." (PMID 40305291, 2025). "Notably, UA upregulated Sirt1 and FOXO1 expressions in tumor tissues, reinforcing its role in modulating pathways critical to tumor suppression." (PMID 40568370, 2025). "SIRT1, a NAD+-dependent deacetylase, influences tumor cell metabolism, apoptosis, and angiogenesis." (PMID 41551597, 2025). "Thus therapeutic inhibition of NAMPT with FK866 or SIRT1 with EX527 led to significant reduction of tumor angiogenesis and suppressed tumor growth." (PMID 40050933, 2025). "The elevated expression of SIRT1 in 67NR primary tumors suggests a tumor-suppressive role in nonmetastatic settings." (PMID 41816745, 2025). "AMPK also regulates NAD+ biosynthesis and is activated by upstream signals such as Liver Kinase B1 (LKB1), Insulin Receptor Substrate (IRS), and sesquiterpenoids; LKB1 is deacetylated by Sirtuin 1 (SIRT1), forming a metabolic feedback loop that supports tumor progression." (PMID 40951358, 2025). "Similarly, in endothelial cells, tumor cell-derived exosomal LYPLAL1-DT downregulated miR-204-5p, resulting in elevated levels of both PFN2 and SIRT1." (PMID 41551597, 2025). "Clinically, elevated SIRT1 expression in NSCLC correlates with a poor response to immunotherapy and shortened patient survival, underscoring its role as a redox-driven regulator of tumor maintenance." (PMID 41008982, 2025). "The novel SIRT1 inhibitor MHY2245 has demonstrated the ability to induce autophagy and inhibit energy metabolism in OC cells via the PKM2/mTOR pathway, leading to reduced tumor growth in preclinical models." (PMID 41300302, 2025). "Notably, CANA exerts tumor-promoting effects through the NAD+ salvage pathway, which recycles nicotinamide into NAD+, and by activating SIRT1 at lower concentrations." (PMID 39940750, 2025). "Updated studies demonstrated that SIRT1 deacetylated FOXO proteins, acting as a tumor activator." (PMID 41300302, 2025). "Specifically, FSP1 promotes mitochondrial biogenesis by activating the sirtuin 1 (SIRT1)/peroxisome proliferator-activated receptor gamma coactivator 1-alpha (PGC-1α) axis, thereby enhancing the metabolic activity and invasive capacity of tumor cells." (PMID 40862825, 2025). "A notable example is represented by miR-22, which can play opposite roles in different scenarios; it suppresses tumorigenesis and favorably contributes to radiotherapy sensitivity by modulating SIRT1, but, conversely, it promotes EMT and tumor stemness by indirectly acting on TET family enzymes." (PMID 40141248, 2025). "Focusing on COAD and READ, SIRT1 expression was consistently lower in tumors compared to normal tissues, although no clear trend of decreasing expression with higher tumor staging was observed (." (PMID 40229278, 2025).
tumor (continued). "SIRT1 induces EMT by modulating related pathways, contributing to increased tumor invasiveness." (PMID 41300302, 2025). "Additionally, SIRT1 deacetylates the coactivator MYST1, enhancing its interaction with AR and NF-κB, which drives aggressive tumor behavior and therapeutic resistance." (PMID 39796040, 2024). "However, NMRGs with significant AUC values (ENPP1, ENPP2, NAMPT, SIRT1, PARP1, NMNAT1, and PNP) were differentially expressed among tumor grades." (PMID 38254798, 2024). "In addition, it has been noted that SIRT1 is significantly and positively correlated with VEGF expression, and SIRT1 can promote tumor angiogenesis and create a favorable environment for tumor growth." (PMID 38180750, 2024). "In terms of SIRT1’s oncogenic role, inhibiting it can disrupt tumorigenesis; for instance, LITAF increases FOXO1 levels, leading to SIRT1 downregulation, which diminishes the stemness and malignant phenotype of tumor cells." (PMID 39403142, 2024). "However, administration of the Sirt1 inhibitor EX527 abolishes the effects of agrimol B. Finally, we establish a tumor-bearing mouse model and find that agrimol B has a synergistic antitumor effect with CDDP." (PMID 38404180, 2024). "The level of AceH3K9, as a mark for lack of SIRT1 activity, increased significantly (P = 0.043) from primary tumours of stage II patients to metastases." (PMID 39494323, 2024). "Our findings revealed that Sirt1 was expressed in tumor tissues, but not in normal tissues, and its high expression was associated with a worse prognosis." (PMID 38427808, 2024). "The interaction between SIRT1 and the TGF-β signaling pathway may affect the EMT process and tumor immune escape." (PMID 39845948, 2024). "To conclude, the overall presented data suggest that IRE1/XBP1s signaling may in some conditions act as a tumor suppressor pathway in AML, in particular through activation of the XBP1s/miR-22/SIRT1 axis." (PMID 38909090, 2024). "The SIRT1/FOXO signaling pathways is demonstrated to participate in multiple crucial mechanisms, which included cell apoptosis, oxidative stress resistance, and tumor progression." (PMID 39014438, 2024). "Furthermore, in KrasG12D/+;Sirt1co/co mice, treatment with cisplatin and erlotinib robustly reduced the tumor burden and increased survival rates compared with those in spontaneous LSL-KrasG12D/+;Sirt1+/+ mice and mice in each single-drug treatment group." (PMID 37779142, 2023). "For example, a key role for SIRT1 as a tumor promoter that inhibits PC formation in CCA cells and induces cell proliferation has been demonstrated by the same group, who also provided a rationale for clinically exploring the use of SIRT1 inhibitors in CCA." (PMID 37510333, 2023). "Mechanistically, NAMPT may modulate SIRT1 and PARP1 activity to regulate stem cell signaling pathways, thus influencing the EMT and tumor cell dedifferentiation." (PMID 38116009, 2023). "Additionally, SIRT1 plays crucial roles in HCC stem cell self-renewal and fosters tumor cell invasiveness." (PMID 36899911, 2023). "In addition, SIRT1 was shown to be a critical downstream target of VIRMA, which fuels tumor metastasis." (PMID 36691046, 2023).
tumor (continued). "This was accomplished by increasing hepatic SIRT1 protein activity, deacetylating SIRT1 targets, decreasing caspase-1 activation, and reducing hepatic inflammation, indicating APO10LA as having anti-inflammatory and anti-tumor effects in MASLD-HCC models." (PMID 38313077, 2023). "In addition, the tumor sphere formation ability of HCT116R and HT29R cells was enhanced in response to SIRT1 overexpression and reduced in response to FOXQ1 knockdown." (PMID 35183223, 2022). "SIRT-1 can inhibit Th17 differentiation by deacetylating STAT3, thereby slowing tumor growth." (PMID 35906622, 2022). "The cytoplasmic SIRT1 colocalizes dsh protein in the cytoplasm and enhances the expression of DNA Methyl-transferase 1 (DNMT1) that promote DNA hypermethylation in the promoter domain of APC, thereby inhibiting its tumour suppressor function." (PMID 36505828, 2022). "However, not only SIRT1 but also NAD-dependent protein deacetylase sirtuin-6 (SIRT6), which simultaneously plays a role as a tumor suppressor and oncogene, can be phosphorylated by CK2." (PMID 36009534, 2022). "Thus, the present study reports that elaiophylin has potent anti-tumor properties in LADC, which effect is likely mediated through suppressing the SIRT1/Nrf2 signaling." (PMID 36497294, 2022). "However, the ways of NR/SIRT1/Notch and NR/SIRT1/FOXO molecular interactions during tumor development still need to be studied in more detail." (PMID 36361882, 2022). "Sirtuin 1 (Sirt1) was found to be the main driver in the regulation of MDSCs differentiation through HIF-1-mediated glycolytic metabolic reprogramming and has an impact on MDSC functions in both immune suppression and promotion of tumor progression." (PMID 36578780, 2022). "However, high levels of SIRT1 were found in some tumours, in which NAMPT activates SIRT1 expression by increasing NAD+ levels and decreasing NAM." (PMID 36078035, 2022). "Furthermore, defects in DNA repair and damage response genes such as RAD51, KU80 SIRT1, NFAT5, and REV3L, or ESCC tumor cells expressed higher CLDN4 to harbor stem-like properties are also the potential CCRT resistance mechanisms." (PMID 35457185, 2022). "Nuclear SIRT1 will bind to the LEF1 lysine residue to deacetylate the present histones regulating the transcription of the downstream targets such as cyclin D1, C-Myc, and surviving, thereby inducing tumour proliferation and migration." (PMID 36505828, 2022). "In lung tissue, cytoplasmic expression of SIRT1 was more extensively expressed in metastatic areas in the metastatic 4TLM compared to non-metastatic 67NR and tumor-free groups." (PMID 36142156, 2022). "These pathway correlations support the hypothesis that NAMPT modulates SIRT1 and PARP1 to control the cellular functions that promote proliferation and stemness pathways, thus regulating the EMT and tumor dedifferentiation." (PMID 33384409, 2021). "The authors found that SIRT1 was overexpressed in various HCC cell lines and tumor specimens." (PMID 34440674, 2021). "We further stained tumor samples with FBXW11, SIRT1, HIC1, and a proliferation marker, Ki-67." (PMID 34642302, 2021). "However, another study showed that SIRT1, SIRT3, and SIRT6 function as the tumor suppressors in RCC." (PMID 34778292, 2021).